BRCA2 (BRCA2 DNA repair associated)
Diseases named in the same sentence as BRCA2 in open-access papers (continued):
Sharing a sentence is not in itself a finding about the gene and the disease.
breast cancer (continued). "Breast cancer driver gene BRCA2 directed the binding of RAD51 recombinase to single-stranded DNA, reduced the binding of RAD51 to duplex DNA, and stimulated RAD51-mediated DNA strand exchange." (PMID 38091511, 2022). "It was estimated that the cumulative breast cancer risk for a 70-year-old woman is up to 87% for BRCA1 and 84% for BRCA2 mutation carriers with corresponding ovarian cancer risks up to 68% and 30%, respectively." (PMID 36246618, 2022). "Approximately 10% of men with breast cancer are genetically predisposed, which, in most cases, is determined by hereditary BRCA1 and BRCA2 mutations." (PMID 35303741, 2022). "His mother suffered from breast cancer, and because of the genetic risk, he was evaluated for breast cancer gene 1 (BRCA1)/breast cancer gene 2 (BRCA2) mutation and was positive." (PMID 37435457, 2022). "Most frequently, a strong genetic predisposition to breast cancers is related to mutations in high penetrance tumor suppressor genes: BRCA1 (BReast-CAncer 1) and BRCA2." (PMID 36230696, 2022). "Women with a primary breast cancer (PBC) diagnosis and a pathogenic germline mutation in the BRCA1 or BRCA2 gene are at increased risk of developing metachronous contralateral breast cancer (CBC)." (PMID 34929424, 2022). "In breast cancer, on the other hand, a more immunosuppressive phenotype of BRCA1-mutated tumors was observed compared to BRCA2-mutated tumors." (PMID 36077694, 2022). "Many experts assume that given the equal proportion of BRCA1 versus BRCA2 mutated breast cancers, and approximately 20% of BRCA1 and 80% of BRCA2 PV are associated with ER+ breast cancers, 50% of all BRCA1/2 mutated breast cancers are of ER+/HER2- subtype." (PMID 35158866, 2022). "The precision obtained for Intrahepatic cholangiocarcinoma was 0.85 and for Non BRCA1/BRCA2 familial breast cancer was 0.89." (PMID 36401182, 2022). "Rare germline variants in the high-risk genes BRCA1 and BRCA2 together with the moderate-risk genes such as PALB2, ATM, CHEK2, and BRIP1 account for about 30% of breast cancer predisposition." (PMID 34755241, 2022). "As BRCA1 and BRCA2 play an important role in HRR and breast cancer risk, their interaction with genes included in our study regarding the investigated outcomes would be of great interest for future studies." (PMID 36139526, 2022). "Hereditary breast cancers account for 5–10% of all breast cancers, and the most common causes of the disease are mutations in the BRCA1/BRCA2 genes." (PMID 36057718, 2022). "Thirty-seven loss-of-function variants (30 distinct variants) were found in 36 breast cancer patients, one of whom carried both BARD1:c.1921C>T and BRCA2:c.3860delA." (PMID 35353237, 2022). "The inherited variation in the genetic sequence of BRCA1, BRCA2 genes accounts for 5% to 10% of all breast cancers and was identified primarily among Black and Hispanic breast cancer patients." (PMID 35269622, 2022). "Further, in pathways curated from chemical and genetic perturbation experiments, we found that the genes were enriched for genes highly positively co-expressed with BRCA1 and BRCA2, two genes well reported to be involved in breast cancer." (PMID 36584096, 2022). "The observation of our study supports the lifelong follow-up in BRCA1 and BRCA2 carriers as breast cancer can be diagnosed as late as approximately 80 years in BRCA2 carriers." (PMID 35469032, 2022).
breast cancer (continued). "In unselected patients with breast cancer aged 35-64 years, pathogenic variants of BRCA1 and BRCA2 were detected in 2.4% and 2.3%, respectively." (PMID 36580360, 2022). "In clinical trials, PARP inhibitors are mainly concentrated in cancer patients with homologous recombination repair defects, including breast cancer and ovarian cancer patients with BRCA1 and BRCA2 mutations (gBRCA1/2m)." (PMID 35963853, 2022). "It has been shown that most hereditary breast cancers are associated with abnormal BRCA1 and BRCA2 genes." (PMID 36359297, 2022). "Mutations in BRCA1 and BRCA2, which cause Hereditary Breast and Ovarian Cancer Syndrome (HBOC), account for around 80% of the 5%–10% of breast cancer cases related to rare mutations." (PMID 35128817, 2022). "In BRCA families the onset of ovarian cancer was later than 40 years, and BRCA2-origin breast cancer was seen as late as 78 years." (PMID 35469032, 2022). "For a long time, breast cancer was regarded as a genetic disorder arising from mutations in key regulatory genes such as BRCA1 and BRCA2." (PMID 36076918, 2022). "In a Swedish study, the prevalence of BRCA1 and BRCA2 PVs was 1.8% of all unselected breast cancer patients." (PMID 35469032, 2022). "The PRSER+ yielded the strongest associations with overall breast cancer risk for BRCA1 (OR = 1.40, 95% CI = 1.07 to 1.83) and BRCA2 (OR = 1.33, 95% CI = 1.16 to 1.52) carriers." (PMID 34320204, 2022). "Breast cancer risk clearly increases with an increased number of first- and second-degree relatives diagnosed as having breast cancer for both BRCA1 and BRCA2 carriers." (PMID 36230696, 2022). "The probability of dying from breast cancer and distant metastases was considerably higher for BRCA1 and BRCA2 mutation carriers." (PMID 36140642, 2022). "There were 34 breast cancer patients with pathogenic variants, 3 with likely pathogenic variants, and 55 with VUS in the BRCA2 gene." (PMID 35918668, 2022). "Out of 34 breast cancer patients assessed, those with BRCA2-001/Short expression in any tumor had significantly worse overall survival compared to patients whose tumors did not express this alternative isoform (p = 0.017, HR = 2.535, 95% CI 1.179–5.45)." (PMID 36344544, 2022). "In the joint analysis of BRCA1 and BRCA2 carriers, men in the uppermost PRSER+ quartile had approximately twofold increased breast cancer risk (OR = 2.10, 95% CI = 1.43 to 3.08) compared with men in the lowest quartile (available online)." (PMID 34320204, 2022). "ATM and CHEK2 are examples of moderate-penetrance genes with lower lifetime risk of developing breast cancer as compared to the high-penetrance genes BRCA1 and BRCA2, and these moderate-penetrance genes account for around 6% of HBC." (PMID 35625741, 2022). "PARP which stands for poly-ADP ribose polymerase, is also a famous target for breast cancer treatment, especially for those who have BRCA-1 and BRCA-2 mutations." (PMID 35927682, 2022).
breast cancer (continued). "At this point, breast cancer 1 (BRCA1), breast cancer 2 (BRCA2), and partner and localizer of BRCA2 (PALB2) proteins interact to promote RAD51 filament assembly and stimulate strand invasion." (PMID 35163621, 2022). "In this study, a screening for physical interactors of BRCA2 identified CDK5RAP3, which emerged as a critical regulator of DNA DSB repair that is associated with breast cancer outcomes." (PMID 35053516, 2022). "We therefore interrogated the whole-genome sequencing data from 560 breast cancers to determine the rearrangement frequency at the genomic loci that require MiDAS repair upon BRCA2 abrogation or aphidicolin treatment." (PMID 36002001, 2022). "Almost 10% of breast cancer cases are hereditary and mostly related to BRCA1 or BRCA2 gene mutations; both were initially characterized and sequenced more than 25 years ago and since then have become the most thoroughly studied genes in cancer biology." (PMID 35402282, 2022). "Increased expression of HR-related molecules, such as RAD51 and BRCA2, has also been observed in canine mammary tumor tissue, but their functional roles in tumor cell lines have not been investigated." (PMID 36548864, 2022). "By contrast, there was a negligible increase in survival among carriers of BRCA1 and BRCA2 aged over 35 years with luminal breast cancer in exon 11 who underwent any secondary prevention strategy compared with surveillance." (PMID 36580360, 2022). "At this threshold, studies of breast cancer using GWAS have missed the association of BRCA1 and BRCA2 (prevalences <<1%), even though they are associated with a lifetime risk of breast cancer in women of 65% and 45%, respectively." (PMID 35275946, 2022). "Women at risk for these persisting major concerns are aged below 35 (BRCA1) or 40 (BRCA2) years, unemployed, lower educated, have a history of breast cancer or a more recent BRCA1/2-PV diagnosis." (PMID 34997316, 2022). "The autosomal dominant conditions most frequently linked to a high risk of breast cancer are hereditary breast and ovarian malignancies brought on by mutations in BRCA1 or BRCA2." (PMID 36140642, 2022). "For other germline risk variants (e.g., ATM serine/threonine kinase [ATM], partner and localizer of BRCA2 [PALB2], and checkpoint kinase 2 [CHEK2]), susceptibility to breast cancer has been estimated to account for less than 50% of cases." (PMID 35025760, 2022). "The responses of patients with breast cancer were driven, in part, by patients with germline mutations in PALB2(gPALB2; encoding partner and localizer of BRCA2) and were correlated with high HRD scores." (PMID 36253484, 2022). "One of the more recent studies is the Olympya trial, where patients with HER2-negative early breast cancer and germline PVs or LPVs in FANCD1/BRCA2 and FANCS/BRCA1 are treated with adjuvant Olaparib." (PMID 36091172, 2022). "At least eight genes were found to be significantly associated with breast cancer risk: BRCA1 (MIM#113705), BRCA2 (MIM#600185), ATM (MIM#607585), BARD1 (MIM #601593), CHEK2 (MIM#604373), PALB2 (MIM#610355), RAD51C (MIM#602774), and RAD51D (MIM#602954)." (PMID 36139699, 2022). "PARP inhibitors, including talazoparib and olaparib, are currently approved for the treatment of HER2-negative advanced breast cancer in patients who harbor a genomic BRCA1 and/or BRCA2 (gBRCA1/2) mutation." (PMID 36253484, 2022). "A few genes including BRCA1, BRCA2, and ATM have been known to be associated with the risk of breast cancer." (PMID 36268271, 2022). "“D” has engaged extensively with (lay) literature on hereditary breast cancer and BRCA2 and asks for genetic testing for the known familial BRCA2 mutation." (PMID 36083315, 2022).
breast cancer (continued). "Mutations in the breast cancer susceptibility genes BRCA1 and BRCA2 confer a high predisposition to breast cancers and other tumour types, including ovarian, pancreatic, and colorectal." (PMID 35806243, 2022). "A recent increase in the use of multi-gene panels to screen for breast cancer-associated gene variants beyond BRCA1 and BRCA2 has started to identify PGVs in additional genes." (PMID 33763779, 2022). "In men, BRCA2 mutations and, less frequently, BRCA1 mutations are established risk factors of breast cancer." (PMID 35656339, 2022). "PRS interactions with age and BRCA1 and BRCA2 pathogenic variant characteristics for BRCA1 and BRCA2 carriers with breast cancer risk and prostate cancer risk." (PMID 34320204, 2022). "Two breast cancer women that are double heterozygotes (DH) for both BRCA1/BRCA2, one ovarian cancer case DH for BRCA1/RAD51C, and another breast and colorectal cancer who is DH for BRCA2/PMS2 were identified in our cohort." (PMID 36232793, 2022). "Recent cumulative risk estimates in high-risk families for developing breast cancer by age 80 years were 72% (95% confidence interval (95% CI, 65–79%)) for BRCA1 and 69% (95% CI, 61–77%) for BRCA2 pathogenic." (PMID 36203093, 2022). "Talazoparib, a PARP inhibitor, is active in germline BRCA1 and BRCA2 (gBRCA1/2)-mutant advanced breast cancer, but its activity beyond gBRCA1/2 is poorly understood." (PMID 36253484, 2022). "Statistically significant pre-post changes were obtained in awareness of mutations in breast cancer predisposition genes BRCA1 and BRCA2, breast density, and lifestyle choices affecting breast cancer risk." (PMID 35209930, 2022). "Three breast cancers (one BRCA1, two BRCA2) developed allele-specific LOH upon recurrence, associated with a significant increase in HRD score." (PMID 36344544, 2022). "The pattern of Breast Cancer Genes 1 (BRCA1) and 2 (BRCA2) mutations in Hereditary Breast Ovarian Cancer (HBOC) families varies widely among different populations." (PMID 36230639, 2022). "Factors associated with persistently high cancer concerns were age below 35 (BRCA1) or 40 (BRCA2), unemployment, previous breast cancer, lower education and a more recent BRCA1/2-PV diagnosis." (PMID 34997316, 2022). "In the general male population, the lifetime risk of developing breast cancer is 0.1%; whereas in BRCA1 mutations it is 1.2% by the age of 70, rising to 6.8% in the case of BRCA2." (PMID 35303741, 2022). "In our material in BRCA2 carriers bilateral breast cancer was more common compared to BRCA1 carriers, but this result was not significant." (PMID 35469032, 2022). "In BRCA1 or BRCA2 mutants, these errors lead to chromosomal re-arrangements and shifts typical of hereditary breast cancers." (PMID 36010882, 2022). "BRCA1 and BRCA2 have been identified in the ovarian cancer cluster region in or near exon 11, and in the breast cancer cluster region in multiple regions other than exon 11 so far." (PMID 36010882, 2022). "The BRCA2 frameshift variant, c.5771_5774del p.(Ile1924ArgfsTer38), was identified in BRB290 who was diagnosed with breast cancer at 26 years and 6 months of age." (PMID 35039564, 2022). "Our data connecting CDK5RAP3 to the BRCA2 pathway suggest a potential therapeutic approach for breast cancer." (PMID 35053516, 2022). "In one meta-analysis, breast cancer risk for mutation in BRCA1 and BRCA2 was 57% and 49% respectively." (PMID 35163783, 2022). "Hereditary breast cancers due to germline mutations in the breast cancer susceptibility genes BRCA1 and BRCA2 are very common." (PMID 35012580, 2022).
breast cancer (continued). "In recent years, a large increase in the use of multigene panel tests for breast cancer associated pathogenic variants (PVs) has expanded the number of potentially actionable PVs beyond BRCA1 and BRCA2." (PMID 33758026, 2022). "Some risk factors are constant, such as age and mutations in the BRCA1 and BRCA2 genes, which are estimated to account for 20% to 40% of inherited breast cancers with harmful mutations in BRCA1 and BRCA2." (PMID 35663041, 2022). "Women with persistently high cancer worry scores were more likely to be below age 35 (BRCA1) or 40 (BRCA2) years, be unemployed, have had breast cancer, be lower educated and have shorter time between BRCA1/2-PV diagnosis and surgery." (PMID 34997316, 2022). "One patient had prior exposure to chemotherapy for breast cancer and two patients with HGSC were later identified to carry germline BRCA2 mutations." (PMID 36311816, 2022). "The current approaches of metastatic breast cancer treatment are tyrosine kinase inhibitor (lapatinib); PARP inhibitors with BRCA1 or BRCA2 gene mutation; CDK4/6 inhibitor (palbociclib); PI3 kinase inhibitors; and immunotherapy (“checkpoint inhibitors”)." (PMID 35454076, 2022). "The gene panels include genes with a well-documented association between a rare-monogenic variant and breast cancer (e.g., BRCA1, BRCA2 and PALB2)." (PMID 34755241, 2022). "The first identified breast-cancer-predisposing genes BRCA1 and BRCA2 are responsible for about 25% of HBOC." (PMID 35625741, 2022). "Mutations of breast cancer gene-1 (BRCA1) and BRCA2 were also analyzed with respect to CDH family gene expressions, which represent breast cancer oncogenes." (PMID 36315446, 2022). "In 3,388 breast cancer patients who underwent genetic testing for 25 genes, nearly half of the pathogenic variants were in the BRCA1 (24%) and BRCA2 (24.5%) genes." (PMID 35785170, 2022). "In breast cancer patients, there were 61.90% (13/21) and 69.57% (16/23) of pathogenic variants were distributed in exon 14 of BRCA1 and exon 11 of BRCA2, respectively." (PMID 35918668, 2022). "Four recurrent loss-of-function variants were detected in 11 African-descended breast cancer cases, BRCA1:c.3331_3334delCAAG, BRCA1:c.211A>G, BRCA2:c.1389_1390delAG and PALB2:c.1671_1674delTATT." (PMID 35353237, 2022). "Pathogenic germline variants (PGVs) in one of the known high-risk breast cancer susceptibility genes e.g. BRCA1, BRCA2, PALB2 confer a high risk of developing breast cancer and are enriched in familial cases." (PMID 33763779, 2022). "The detection of PVs in BRCA1 and BRCA2 was, as expected, strongly correlated with breast cancer pathology and family history." (PMID 33758026, 2022). "A small proportion of breast cancer has a familial predisposition, and genetic mutations such as BRCA1, BRCA2, and ATM can significantly increase the incidence of this type of cancer." (PMID 36473847, 2022). "In human cells, a battery of genes including the breast cancer susceptibility genes BRCA1 and BRCA2 work to favor most DSB repair towards error-free pathways." (PMID 36530474, 2022). "BRCA1 compared to BRCA2 result was only a trend, most likely due to the low number of breast cancer incidences." (PMID 35469032, 2022). "Overall risk for breast cancer and ovarian cancer is 55–70% and 40–45% for BRCA1 mutant carriers, respectively, and 45–70% and 15–20% for BRCA2 mutant carriers, respectively." (PMID 35163129, 2022). "Prospective studies have shown that mastectomy reduces the risk of breast cancer by 90% or more, with a residual risk of 1% to 2% in BRCA1 and BRCA2 mutation carriers." (PMID 36397405, 2022). "Especially mutations in BRCA1/FANCS and BRCA2/FANCD1 caused ovarian cancer and breast cancer in women." (PMID 36685883, 2022). "The possibility of late breast cancer onset in BRCA2 carriers supports the lifelong follow-up in BRCA carriers." (PMID 35469032, 2022).